VIM (vimentin)
Diseases named in the same sentence as VIM in open-access papers (continued):
Sharing a sentence is not in itself a finding about the gene and the disease.
gastric cancer (continued). "The results of this study showed that TGFβ1, TGFβ2 and TGFβ3 were positively correlated with EMT, CDH2, VIM and ZEB1 and significantly negatively correlated with CDH1 in multiple gastric cancer datasets." (PMID 36119489, 2022). "There are various markers for gastric cancer CTCs; for the epithelial subtype, they include EpCAm, cytokeratin (CK): CK8, CK18, and CK19 and for the mesenchymal subtype, they include vimentin and twist." (PMID 36428707, 2022). "It was previously reported that LINC00473 suppressed migration and invasion of gastric cancer cells through regulating expression of Matrix metalloproteinase (MMP)‐2, MMP‐9, E‐cadherin, and Vimentin." (PMID 35600648, 2022). "Primary CAFs and NFs were isolated from paired gastric cancer tissues and adjacent normal tissues and identified by immunofluorescence staining and western blot analysis for FSP-1, α-SMA, FAP, and vimentin expression." (PMID 35864535, 2022). "Then, we investigated the correlation of TNC and VM with EMT markers in gastric cancer cells and found that TNC was positively correlated with N-cadherin, Vimentin, MMP2/9 and negatively related to E-cadherin, consistent with previous research." (PMID 34588421, 2021). "Dihydromyricetin (DHM) up-regulates E-cadherin and down-regulates Vimentin through the JNK/MMP-2 pathway, inhibiting the migration and invasion of gastric cancer cells." (PMID 34422902, 2021). "In gastric cancer cells with NFE2L3 knockdown, E-cadherin expression was significantly upregulated, whereas vimentin and N-cadherin expression was inhibited." (PMID 34783304, 2021). "Nuclear vimentin has also been proposed as a metastasis and prognosis biomarker on paraffin-embedded nasopharyngeal carcinoma biopsies, highlighting the metastatic potential and aggressiveness of gastric cancer, even on AGS cells, that could represent early-stage/low-grade tumors." (PMID 34452195, 2021). "In order to clarify the role of EMT and distant metastasis, we first analyzed the mRNA expression of VIM, CDH1, S100A4 and EPCAM in human gastric cancer samples from the Cancer Genome Atlas (TCGA) data." (PMID 33535187, 2021). "For example, the increase of miR-1275 expression regulates the expression of vimentin/E-cadherin by directly inhibiting the expression of JAZF1, thereby inhibiting the metastasis of gastric cancer." (PMID 34422902, 2021). "For example, circNHSL1 served as an oncogenic circRNA in progression and metastasis of gastric cancer through the circNHSL1/miR-1306-3p/SIX1/Vimentin regulatory gene network; circDONSON promoted progression and development of GC cells via the NURF complex-dependent activation of SOX4 signaling." (PMID 32386516, 2020). "A study in gastric cancers revealed that CREPT increases cell migration by regulating E-cadherin, vimentin, N-cadherin, and matrix metalloproteinase 1 (MMP-1) expressions." (PMID 31877646, 2019). "Vimentin levels were positively correlated with lymph node metastasis and TNM stage in gastric cancer patients." (PMID 30974047, 2019). "In gastric cancer, high PBX3 expression leads to the decrease in E-cadherin expression and increase in N-cadherin, vimentin, and MMP-9 expression by promoting EMT via AKT signaling pathway." (PMID 31547193, 2019). "JMJD2B inhibition attenuated β-catenin recruitment to the gene promoter of vimentin, an EMT marker, inducing a decrease in gastric cancer metastasis." (PMID 29700375, 2018). "Multiple downstream targets including vimentin and FSCN1 have been identified to mediate EMT induced by TEAD4 in colorectal cancer and gastric cancer." (PMID 30459528, 2018). "Further, we showed that overexpression of TSP50 up-regulated mesenchymal maker Vimentin, EMT related transcript factor Twist and down-regulated epithelial marker E-Cadherinin in gastric cancer cells." (PMID 29361914, 2018).
gastric cancer (continued). "Our results revealed that silencing DAB2IP reduced E-cadherin expression but increased vimentin expression at both protein and mRNA levels, indicating that DAB2IP exerts a crucial role in modulating EMT in gastric cancer cells." (PMID 29743885, 2018). "UCA1 has also been shown to regulate EMT in Gastric Cancer as, silencing of UCA1 resulted in decreased levels of vimentin and snail, with concomitant elevated levels of E-cadherin." (PMID 28430163, 2017). "It has been reported previously that CTNND1, EZH2, BCL2L2, CDH2, VIM, and EGFR have positive correlation to proliferation, invasion, and poor prognosis of gastric cancer." (PMID 28694563, 2017). "Vimentin (VIM) is a famous EMT marker that promotes tumor invasion and drug resistance in ovarian cancer, colon cancer, and gastric cancer." (PMID 28694563, 2017). "We found a decreased expression of the epithelial markers CDH1, EpCAM, and increased expression of the mesenchymal markers CDH2, Vimentin, ZEB1, Snail, MMP14 and Twist in un-captured cells in gastric cancer cell lines AGS, SGC7901 and BGC-823." (PMID 27654478, 2016). "In gastric cancer cells cocultured with CagA expression plasmid, CagA activated TWIST1 and vimentin expression, and inhibited E-cadherin expression by downregulating PDCD4." (PMID 25144746, 2014). "The present study determined that the combination of alterations in the protein expression of vimentin, E-cadherin, and CD44 was the most effective prognostic factor in gastric cancer." (PMID 25441488, 2014). "We examined the effect of increased or decreased RUNX3 expression on the invasion potential of human gastric cancer cells and the expression of the EMT molecules vimentin and E-cadherin." (PMID 24447545, 2014). "For example, patients diagnosed with vimentin-positive gastric cancer exhibit a significantly poorer prognosis compared to those with vimentin-negative gastric cancer." (PMID 40061451, 2025). "For instance, previous studies using direct co-cultures of breast or gastric cancer cells with bone marrow-derived MSCs identified an upregulation of EMT markers, including vimentin, N-cadherin, Twist, and Snail, while observed reduced expression of E-cadherin 61,62." (PMID 40083939, 2025). "Furthermore, the expression of the mesenchymal marker vimentin was notably reduced in USP15‐knockdown cells, which is consistent with prior reports in gastric cancer and glioblastoma." (PMID 40762380, 2025). "Furthermore, western blot was used to detect the E-cadherin, N-cadherin and Vimentin in different groups, and to evaluate the effect on EMT in gastric cancer cells." (PMID 38698487, 2024). "Indeed, reducing NDRG1 levels in gastric cancer cells led to increased E-cadherin expression and decreased vimentin expression, indicating a link between high NDRG1 levels and the metastatic potential of gastric cancer cells." (PMID 39199357, 2024). "Radioresistant gastric cancer models (AGSR and NCI-N87R) were developed and combined with 8-shogaol and radiation (2 Gy) to overcome radioresistance via the upregulation of N-cadherin and vimentin and the downregulation of E-cadherin." (PMID 39796030, 2024). "Similarly, in gastric cancer, activation of the CXCL12/CXCR4 axis via the STAT3 pathway induces downregulation of E-Cadherin and upregulation of N-Cadherin, Vimentin, and Snail, enhancing EMT, migration, and the invasiveness of gastric cancer cells." (PMID 38920657, 2024). "Additionally, we discovered that LAD1 can promote chemoresistance in gastric cancer in vitro and in vivo, LAD1 targeting can promote chemosensitivity, and LAD1 can stabilize Vimentin by reducing MAEA-mediated ubiquitination." (PMID 37718450, 2023). "In gastric cancer cells, CORO1C expression facilitated cancer cell aggressiveness (e.g., cell viability, colony formation, and metastasis) by positively regulating cyclin D1 and vimentin expression." (PMID 37239355, 2023).
gastric cancer (continued). "Furthermore, we found that PCBP1 overexpression contributes to up-regulation of mesenchymal marker vimentin while down-regulation of epithelial marker E-cadherin both in-vitro and in-vivo, which reversed C12orf48-mediating EMT in gastric cancer." (PMID 35100974, 2022). "Western blot analysis of four gastric cancer cell lines revealed that SH-10-TC cells possessed a mesenchymal phenotype, as they were positive for N-cadherin and vimentin, and negative for E-cadherin." (PMID 35723363, 2022). "In gastric cancer cells EZH2 promotes EMT, upregulates Vimentin and downregulates E-cadherin." (PMID 36316365, 2022). "Knockdown of FGL1 could significantly increase the E-cadherin level of tumor cells and reduce the expression levels of vimentin and N-cadherin in tumor tissues, suggesting that FGL1 could promote the EMT process of gastric cancer." (PMID 35273912, 2022). "Interrogation of CCLE database revealed that FZD5 is positively correlated with epithelial-related factors CDH1 (E-cadherin), OCLN (Occludin), EPCAM and ELF3, while negatively correlated with mesenchymal-related factors VIM (Vimentin), SNAI2 (Slug), ZEB1 and ZEB2 in 37 gastric cancer cell lines." (PMID 33618713, 2021). "Eukaryotic translation initiation factor 5A2 (EIF5A2) (by up-regulating epithelial markers E-cadherin and β-cadherin, down-regulating mesenchymal markers Vimentin and N-cadherin mediate the EMT process to regulate the resistance of gastric cancer cells to cisplatin." (PMID 34422902, 2021). "In the current study, we overexpressed Mist1 and found that E-cadherin was upregulated, while the expression of N-cadherin, Snail and Vimentin were decreased, indicating that Mist1 could inhibit EMT in gastric cancer cells." (PMID 34149921, 2021). "High levels of ZEB2 have previously been reported to promote epithelial-mesenchymal transition (EMT) of gastric cancer cells via regulation of expression of CDH1 (E-cadherin) and other EMT markers, such as VIM (vimentin) and matrix metallopeptidases (MMP2 and MMP9)." (PMID 33806113, 2021). "SDF-1/CXCR7 also downregulated E-cadherin expression but upregulated N-cadherin, vimentin and Snail expressions, suggesting that SDF-1/CXCR7 could promote the development of EMT in gastric cancer cells." (PMID 34858476, 2021). "Furthermore, WB detection also confirmed that E-cadherin protein elevated while vimentin, fibronectin, and Sox4 protein declined, suggesting that MIR4435-2HG can inhibit EMT in gastric carcinoma cells by controlling miR-138-5p/Sox4 axis." (PMID 34532282, 2021). "Similarly, in gastric cancer cells, FOXA1 regulates the EMT in cancer cells, by inducing the E-cadherin expression and decreasing the vimentin protein level." (PMID 32685483, 2020). "Finally, the expression of four hub genes (ERBB2, VIM, EGR1, and PSMB8) was found to be related to the prognosis of HER2-positive (HER2+) gastric cancer." (PMID 31949544, 2019). "In gastric cancer cells, SOX9 promotes EMT by activating the Hippo-YAP pathway and SOX9 silencing rescued the expression of E-cadherin and downregulated mesenchymal markers N-cadherin, vimentin and SNAIl." (PMID 31547193, 2019). "Furthermore, we demonstrated that circNHSL1 promotes invasion and metastasis of gastric cancer cells in vitro and in vivo by targeting the miR-1306-3p/SIX1/Vimentin axis." (PMID 31438963, 2019). "On the other hand, Vimentin is a widespread mesenchymal intermediate filament which results in adhesion and migration of activated cells and is key for the aberrant EMT activation in gastric cancer." (PMID 31640627, 2019). "Multi-color immunofluorescence analyses of EpCAM, vimentin, and DAPI were performed by measuring the fluorescence intensities of respective target molecules in 3D-cultured human gastric cancer cell-lines (AGS, KATOIII, NCI-N87, MKN-45, and SNU-216) on a micropillar chip." (PMID 31850215, 2019).
gastric cancer (continued). "Together, ERBB2, VIM, and PSMB8 may be effective targets in gastric cancer, but more experimental investigations and clinical trials are needed." (PMID 31949544, 2019). "In view of the important role of EMT in tumor metastasis during tumor progression, we explored the effect of DAB2IP on EMT progress and revealed that DAB2IP can modulate the expression of EMT marker E-cadherin and vimentin in AGS and SGC7901 gastric cancer cells." (PMID 29743885, 2018). "Furthermore, bufalin inhibited ASCL2 expression and down-regulated the expression of invasion-related genes such as MMP2, MMP9, and vimentin, thereby suppressing epithelial-mesenchymal transition (EMT) in gastric cancer." (PMID 29805736, 2018). "Our results indicated that ICG-001 reversed the decrease of E-cadherin, and the increase of N-cadherin and vimentin in MKN45/R and NCI N87/R cells, manifesting that inhibition of β-catenin signaling by ICG-001 reverses EMT in trastuzumab-resistant gastric cancer cells." (PMID 29986466, 2018). "Subsequently, overexpression of miR-30a inhibits the expression of Snail and Vimentin but promotes E-cadherin expression, which implies that miR-30a could enhance cisplatin sensitivity by inhibiting EMT in gastric cancer cells." (PMID 30158978, 2018). "Colon cancer associated transcript 2 (CCAT2) appears to promote EMT, as lncRNA CCAT2 knockdown leads to increased E-cadherin and decreased vimentin levels in gastric cancer cells and, additionally, CRC cells expressing higher levels of CCAT2 display increased vimentin expression." (PMID 28430163, 2017). "In this study, we found that overexpression of ERp29 could increase the epithelial marker E-cadherin and decrease the mesenchymal cell markers N-cadherin and Vimentin, implying that ERp29 overexpression may suppress EMT in gastric cancer." (PMID 29108263, 2017). "We found that MLN4924 increased the expression of E-cadherin, an epithelial biomarker in a dosage-dependent manner in both gastric cancer cell lines, without affecting the levels of mesenchymal markers N-cadherin and Vimentin." (PMID 27063292, 2016). "In most cases, the expression of Gal-1 and vimentin were significantly higher in the gastric cancer tissues than the matched non-cancerous tissues (P < 0.05)." (PMID 27835885, 2016). "In our study, we found that transfection of HIF-1α-induced-miR-421 significantly down regulated the epithelial biomarker E-cadherin and up regulated N-cadherin, Fibronectin, Vimentin, Snail, Slug, Twist, MMP-2, and MMP-9 in cisplatin treated gastric cancer cell lines." (PMID 27016414, 2016). "A highly significant negative correlation between RUNX3 and vimentin protein was observed in these gastric cancer samples (P < 0.0001)." (PMID 24447545, 2014). "In this study, in order to clarify whether FSIP1 is related to gastric cancer cells metastasis, we explored the effect of knockdown of FSIP1 on EMT-related markers, and we found that N-cadherin protein level and vimentin protein level were decreased in sh-FSIP1 cells." (PMID 38737444, 2024). "In the same way, we found that COL4A1 silence downregulated the expressions of Ki67, PCNA, MMP2, MMP9, N-cadherin and Vimentin but promoted E-cadherin expression in MKN-45 cells, revealing that COL4A1 silence could help to suppress the proliferation, metastasis and EMT in gastric cancer." (PMID 35297303, 2022). "Neutrophils in the stroma of gastric cancer (GC) produce IL17a and CXCL5 both promoting EMT, indicated by upregulation of VIM and ZEB1, whereas CDH1 is repressed." (PMID 34459003, 2021). "NUAK1-downregulation increases E-cadherin expression and decreases vimentin in hepatocellular carcinoma (HCC) cells and gastric cancer (GC) tissue." (PMID 34685740, 2021).
gastric cancer (continued). "To understand more about the localization patterns of epithelial and mesenchymal markers on gastric cancer, we performed a series of immunocytochemistry experiments on GES-1 and AGS cells, using proper antibodies to detect pan-cytokeratin as epithelial protein, and vimentin as mesenchymal protein." (PMID 34452195, 2021). "The effect of NOX-enhanced tumor metastasis in gastric cancer could be mediated through regulation of EMT markers, including MMPs, fibronectin, vimentin, snail, zeb1, and E-cadherin 62, which is consistent with our findings that MMP expression was essential for NOX4-regulated CRC cell invasion." (PMID 32641980, 2020). "In our work, we found that FOXS1 expression was inversely correlated with the expression of epithelial markers (E-cadherin) and positively correlated with the expression of mesenchymal markers (vimentin and N-cadherin), indicating that FOXS1 could induce EMT in gastric cancer cells." (PMID 30918291, 2019). "Besides, the expression levels of SPOCK1, E‐cadherin, Slug and Vimentin were detected in gastric cancer tissues and in adjacent normal gastric mucosas of 102 patients with gastric cancer by immunohistochemical staining." (PMID 28940639, 2018). "In cancer patients, “mesenchymal CTCs” (epithelial marker CK/E-cadherin negative, mesenchymal marker vimentin/N-cadherin positive) are chemoresistant, which keeps in agreement with our previous report indicating the majority of gastric cancer CTCs were CK18- and chemoresistant." (PMID 25909226, 2015). "To further determine whether miR-30a directly targets vimentin mRNA in gastric cancer cells, we inserted the full-length 3′ UTR of vimentin into the pMIR-REPORT luciferase vector (pMIR-Vim) and investigated the effect of miR-30a on the luciferase activity of pMIR-Vim." (PMID 24447545, 2014). "In gastric cancer (GC), SIRT1 silencing or inhibiting its activity by EX527 enhances expression of FOXO1, pro-apoptotic BAX, and E-cadherin, whereas the expression of Ki67, Cyclin D1, anti-apoptotic Bcl-2, Vimentin, MMP-2 and MMP-9 are downregulated, suggesting SIRT1 involvement in GC progression." (PMID 34769241, 2021). "For RUNX3, a tumor suppressor role has been reported in gastric cancer, contingently via a mechanism involving negative regulation of MMP9 and vimentin." (PMID 38630262, 2024). "In order to better identify gastric cancer patients with EMT, EMT and non-EMT patients were distinguished by combining the expression levels of VIM (high expression), CDH1 (low expression), S100A4 (high expression) and EPCAM (low expression)." (PMID 33535187, 2021). "The treatment of gastric cancer HGC-27 cells with non-toxic concentrations of polyacetylene 1 significantly suppressed EMT markers, namely, Vimentin and Snail, while it enhanced the level of E-cadherin, indicating that polyacetylene 1 could reverse the EMT process." (PMID 36838824, 2023). "The results suggested the EMT maker included Snail and Slug, but not Vimentin, were significantly increased in cells overexpressing wild-type or mutant HPA, suggesting that EMT may also play a key role in nonenzymatic HPA-mediated gastric cancer development." (PMID 35970822, 2022).